NOTCH1 (notch receptor 1)
Diseases named in the same sentence as NOTCH1 in open-access papers (continued):
Sharing a sentence is not in itself a finding about the gene and the disease.
tumor (continued). "To determine the role of Notch1 in tumor cell intravasation-directed transendothelial migration (iTEM) activity, we either depleted Notch1 in tumor cells with siRNA or inhibited Notch signaling with DAPT and quantified the tumor cell iTEM activity in the presence and absence of macrophages." (PMID 27901093, 2016). "There was a significant decrease in the number of circulating tumor cells in mice that were treated with the Notch1 blocking antibody compared to control treated mice, consistent with the idea that transendothelial migration is involved in CTC (Circulating Tumor Cells) number." (PMID 27901093, 2016). "However, NOTCH1 exerted tumor suppressor function in a model of K-RAS-induced pancreatic ductal adenocarcinoma." (PMID 27938406, 2016). "Pre-clinical studies show encouraging results with GSIs treatment of T-ALL cell lines resulting in the rapid clearance of activated Notch1 and the transcriptional down-regulation of its target genes, with consequent decrease in tumor cell growth and proliferation due to G1 cell cycle arrest." (PMID 26934331, 2016). "This is similar to that previously revealed for ras‐transformed p21 knockout keratinocytes 32, suggesting that NOTCH1 and p21 may overlap to perform their tumor suppressing functions." (PMID 27228302, 2016). "Several studies using SCLC cell lines have suggested a tumor suppressor role for NOTCH1." (PMID 26491213, 2015). "MiR200 could inhibit Notch1 expression, and cells tumor formation capacity and self-renewing ability decreased." (PMID 25943311, 2015). "A previous study reported that NOTCH1 signalling suppresses tumour growth of HCC41." (PMID 25985737, 2015). "Hypoxia may also have a significant influence on macrophage/DC function, in addition to promoting cancer cell stemness and tumor survival through HIF-1α/Notch-1 signaling." (PMID 26343197, 2015). "Importantly, Fbxw7α is considered a tumor suppressor protein primarily because Fbxw7α targets multiple well-known oncoproteins, including Cyclin E, c-Myc, c-Jun, Mcl-1, and Notch-1 for ubiquitination-mediated destruction." (PMID 26461473, 2015). "In this screen, Notch1 harbours insertions in 130 independent tumour samples." (PMID 25721899, 2015). "We saw a trend toward longer PFS in patients whose tumors bore lower expression of NOTCH1, most likely because NOTCH1 expression might be involved in tumor resistance to bevacizumab." (PMID 26394830, 2015). "In addition, the MAb treatment significantly inhibited the genes associated with the Notch pathway and stemness and cleaved Notch1 expression in the resected tumor xenografts." (PMID 26046801, 2015). "Despite the substantial data of Notch1 in tumorigenesis and tumor cell survival, association of Notch1 expression levels and patterns with tumor progression in terms of tumor size and metastasis remains to be delineated." (PMID 25653136, 2015). "The loss of PTEN function, particularly the inactivation of both alleles, is observed primarily in tumours without the hyper-activated combination of Notch1 5′ deletion plus PEST domain mutation." (PMID 26125582, 2015). "This study showed overexpression of active Notch1 having the ability to immortalize HSCs, which could lead to neoplasia." (PMID 25711903, 2015). "Additionally, Notch1 and Sonic hedgehog (SHH) are also closely associated with the differentiation of various tumor cells." (PMID 26563263, 2015). "Indeed, on one hand most NOTCH1 mutations found in the recent NGS approaches in HNSCC were predicted to result in loss of function and therefore point towards a tumor-suppressive role." (PMID 25836654, 2015).
tumor (continued). "Patients with higher NOTCH1-expressing tumors in the subgroup with early pathological tumor stages had significantly better survival than those with a low expression, and multivariate analysis indicated that NOTCH1 expression was an independent prognostic factor in this subgroup." (PMID 25954607, 2015). "The findings support our hypothesis that inactivated Notch1 may serve as a context-dependent restrictive factor of tumor cells to local-regional spread." (PMID 25653136, 2015). "We observed that tumor-induced decrease in the expression of Notch receptors, Notch1, Notch2, Notch3 and Notch4, as well as ligands Dll1, Dll4 and Jagged1 in splenocytes of 4T1HA and RencaHA tumor-bearing mice could be reversed by treatment with bortezomib." (PMID 26431276, 2015). "However, re-expression of active Notch1 or PIP in Met1 tumor cells rescued the growth deficit in a Postn-null environment, suggesting that the loss of Postn selects for an AR-dependent pathway." (PMID 25592291, 2015). "Notch1 5ʹ deletions detected by CGH were more frequently associated with tumours that did not harbour trisomy 15 (7/10, 70%) over those with trisomy 15 (5/21, 24%, P = 0.021, Fisher’s Exact) suggesting a redundancy between the Notch1 and Myc pathways." (PMID 26125582, 2015). "Also, some functional studies suggest that NOTCH1 is an oncogene, whereas others suggest it is a tumor suppressor gene." (PMID 26353933, 2015). "However, Notch1 in distinct expression patterns and activation status with tumor progression remains to be defined in NSCLC." (PMID 25653136, 2015). "Furthermore, Notch1 protein expression was positively correlated with tumor stage and pathology grade (high expression Notch1 in poorly differentiated carcinoma)." (PMID 26650241, 2015). "Since JNK2 protein is present in both basal and luminal lineages, it could suppress Notch1 in both stem and progenitor type tumor cells." (PMID 25970777, 2015). "NOTCH1 expression was evaluable in 133 of the 142 primarily resected tumor specimens." (PMID 25954607, 2015). "Furthermore, knockdown of Msi1 lead to mitotic catastrophe in tumor cells and resulted in inhibition of Notch1, indicating that Msi1 regulates Notch signaling." (PMID 26270561, 2015). "Furthermore, KLF9 was shown to function as a suppressor of tumor-initiating stem cells by directly suppressing Notch1 signaling." (PMID 25880754, 2015). "Another downstream target of Notch1 is Hes1, which contributes to tumor progression." (PMID 25879451, 2015). "Interestingly, Fbw7 is often referred to as a tumor suppressor for its roles in regulating the degradation of potent oncogenes such as Cyclin E, c-Myc, c-Jun, Mcl-1, mTOR and Notch-1." (PMID 24912918, 2014). "Moreover, cytoplasmic ADAM10 and activated Notch1 were colocalized within these giant cells, suggesting that ADAM10/Notch1 signaling was activated in these angiogenic tumor cells." (PMID 24548763, 2014). "Experimental evidence demonstrates that Notch inhibition by either mAb against Notch1 or Notch2 appears to have anti-tumor and anti-angiogenic effects with limited gastrointestinal toxicities while simultaneous inhibition of Notch1 and 2 lead to gastrointestinal toxicity, as seen with many GSIs." (PMID 24959528, 2014). "To further investigate whether KPT-251 down-regulates Notch1 in vivo, we examined Notch1 expression in tumor tissues obtained from KPT-251-treated animals." (PMID 24899509, 2014). "Fbw7 has been recently shown to exert its anti-tumor effects through degradation of Notch1." (PMID 24899509, 2014).
tumor (continued). "As both, NOTCH1 and DLL1, are predominantly localized in more differentiated cells in the normal urothelium, their decreased expression in tumours may conceivably reflect to some extent the loss of this differentiated cell population." (PMID 25167871, 2014). "Notch1 is required for tumor initiation in the KRAS-driven lung ADC mouse model." (PMID 25004243, 2014). "In addition, Notch1 expression was significantly higher in the tumor tissues than that in the adjacent normal mucosa tissues, as well as in the metastatic patients compared with the non-metastatic patients." (PMID 24932308, 2014). "Furthermore, Notch1 expression was significantly increased in the tumor tissues compared with the adjacent normal mucosa tissues, as well as in patients with metastases than in patients without metastases." (PMID 24932308, 2014). "Furthermore, Demarest and colleagues demonstrated that c-Myc expression cannot fully rescue a T-ALL tumor when Notch1 expression is extinguished in a transgenic mouse model indicating that tumor maintenance is dependent on oncogenic Notch signaling." (PMID 25072021, 2014). "Depletion of visfatin or Notch1 reduced the ability of tumor cells to form colonies in soft agar." (PMID 24970818, 2014). "To determine whether the visfatin-Notch1 axis plays a role in tumor growth, we used the soft agar assay." (PMID 24970818, 2014). "However these findings disagree with those studies where tumor suppressor properties of Notch1 are suggested." (PMID 23409141, 2013). "An ideal biomarker test would detect NICD1 within tumor cells directly, regardless of the underlying mechanism of NOTCH1 activation." (PMID 23825651, 2013). "Moreover, it is suspected that ligand-mediated NOTCH1 activation also contributes to tumor cell growth and survival, and such tumors would go undetected by genetic screening." (PMID 23825651, 2013). "Additionally, selective blocking of Notch1 with antibodies inhibits tumor growth by a mechanism consistent with that of Dll4 inhibition, namely by promoting abnormal growth of vessel sprouts that do not perfuse tissues." (PMID 23601498, 2013). "The expressions of Notch1 were statistically correlated with tumor differentiation status." (PMID 24312514, 2013). "The binary properties of Notch-1 which behaves as either an oncogene or a tumor suppressor may possibly depend on the developmental stages or various histological types in LAD patients." (PMID 24423157, 2013). "Similarly to our previous studies, following the knockdown of DCLK1, we also observed inhibition of NOTCH1 via miR-144 in AsPC-1 tumor xenografts." (PMID 24040120, 2013). "Furthermore, in a study evaluating 87 resected HCC tumors, Notch1 protein (cytoplasmic) was upregulated in 89% of tumor specimens, when analyzed using immunohistochemical staining and western blot." (PMID 24024180, 2013). "We therefore analysed MigR1 control and Fli-1 tumour cells for the presence of 5′ Notch1 deletions." (PMID 23667468, 2013). "However, several “experiments of nature” in our tumor set point to a role for intranodal factors in NOTCH1 activation." (PMID 23825651, 2013). "Therefore, we chose to analyse tissues from both MigR1 control and Fli-1 tumour cells for the presence of intracellular NOTCH1 protein by flow cytometry." (PMID 23667468, 2013). "We then tested the suppression of Notch1 by its siRNA in HeLa-S3 tumor cells." (PMID 23071601, 2012). "Furthermore, use of DAPT increased the expression of ROCK1 and 2, supporting the idea that Notch1 normally controls these genes in keratinocytes to prevent tumour progression." (PMID 22583596, 2012). "The results showed that aside from maintaining the growth of normal kidney cells, Notch1 could also stimulate the growth of tumor cells which may facilitate the progression of early stage ccRCC." (PMID 22506064, 2012). "Next we analyzed the mRNA expression of Notch1 and Jagged1 on different tumor stages of ccRCC." (PMID 22506064, 2012).
tumor (continued). "To determine whether NOTCH1-mediated mammary tumorigenesis is driven by a rare tumor-initiating cell, we performed an in vivo limiting-dilution assay." (PMID 22992387, 2012). "The Notch1- siRNA/H101 group, however, had an enhanced anti-tumor effect." (PMID 23071601, 2012). "Since tumor size had been reported to be a risk factor in the metastasis of T1 stage RCC, we analyzed the correlation of tumor size and relative mRNA expression of Notch1 and Jagged1 in 23 T1 stage ccRCC samples." (PMID 22506064, 2012). "Finally, curcumin treatment down-regulate the expressions of Notch-1 specific microRNAs miR-21 and miR-34a, and upregulated tumor suppressor let-7a miRNA." (PMID 22363450, 2012). "Taken together, we postulated that Notch1 may stimulate the growth of tumor cells resulting larger tumor size and finally metastasis of early stage ccRCC." (PMID 22506064, 2012). "To determine whether NOTCH1 inhibition interferes with or prevents disease recurrence, we treated six tumor-bearing mice with doxycycline for 28 days, and then removed dox from the drinking water and monitored the animals for disease recurrence." (PMID 22992387, 2012). "Previous work by our group has identified Notch1 as a tumor suppressor in a mouse model of PDAC." (PMID 23284900, 2012). "Interestingly, increased ErbB-2 expression in tumour-initiating cells was shown to be Notch-1 dependent." (PMID 21847123, 2011). "Although Notch signaling and Snail are both widely considered tumor-promoting factors, our findings indicate that the individual oncogenic contribution of Notch1 and Snail in malignant systems should be interpreted carefully, particularly when they are conjointly expressed." (PMID 22128911, 2011). "Two major changes following DLL4/NOTCH1 blockade might contribute to the defective function of the tumor vasculature: impairment of lumen formation and promotion of a chaotic vascular network." (PMID 21824400, 2011). "Similarly, Notch1 expression in tumor cells was significantly correlated with lymph nodes metastasis (χ2 = 10.162, P = 0.001), LVD (χ2 = 6.362, P = 0.010), VEGF-C expression (χ2 = 17.176, P = 0.001), and podoplanin expression (χ2 = 6.877, P = 0.008)." (PMID 21939555, 2011). "We hypothesize that in cancer Notch3 is important for tumor survival, whereas Notch1 mediates the response to hypoxia through the regulation of angiogenesis." (PMID 22074495, 2011). "This may be related to acquisition of additional mutations in patients who have received several therapies and may relieve tumor cells from Notch1 addiction." (PMID 22128846, 2011). "Furthermore, we have shown that deletion of c-Myc at the CD4+CD8+ stage of T cell development prevented tumor formation induced by Notch1." (PMID 22111016, 2011). "Our finding that Notch1 expression is negatively associated with high expression of VEGF-C and VEGFR-3 in ESCC may indicate that down-regulation of Notch1 signaling contributes to tumor-induced lymphangiogenesis." (PMID 21939555, 2011). "Therefore it appears plausible that Notch1 is also the predominant mediator of Dll4-Notch signaling in the tumor vasculature, although Notch4 has also been described as a receptor specifically expressed by endothelial cells." (PMID 21923938, 2011). "Taken together, our findings imply that Notch1 and NF-κB signaling have counter-acting roles in tumor-induced lymphangiogenesis in ESCC, and suggest that Notch may differentially regulate physiological and tumor-induced lymphangiogenesis." (PMID 21939555, 2011). "We further investigated the roles of Notch1 and Notch2 in MB tumor biology in which their opposite effects have already been reported: Notch1 activity inhibits cell growth and induces apoptosis, while Notch2 up-regulates Hes1 expression, which promotes cell proliferation." (PMID 21931765, 2011). "Do Notch1 and RhoC regulate similar function during tumour progression?" (PMID 19953094, 2010). "We thus propose RhoC as downstream effector of Notch1 during tumour progression." (PMID 19953094, 2010).
tumor (continued). "Expression of Notch1 and Notch3 was elevated in Hes1tg tumors A, C and D, as well as Id1tg tumor C." (PMID 19688092, 2009). "In human cancer cells, Notch1 acts as either a tumor suppressor or an oncogene." (PMID 20069043, 2009). "In addition, PTEN, SMAD4, and NOTCH1, are known tumor suppressors whose transcript or protein levels are decreased in tumors." (PMID 19922656, 2009). "The relationship we have uncovered between Notch and Armadillo in Drosophila is reminiscent of that described in the skin of mice where targeted removal of Notch1 results in high levels of activated ß-catenin that prime the cells for the development of tumours." (PMID 19668359, 2009). "Many studies suggest a role for Notch1 in keratinocytes as a tumor suppressor." (PMID 19828018, 2009). "For example, Ikaros (Zfpn1a1) and Notch1 insertions frequently co-occur within the same tumor." (PMID 18485879, 2008). "In fact, since NOTCH1 can be regarded either as an oncogene or as a tumor suppressor, depending on the cellular context, this rule may also apply to NOTCH2." (PMID 17593975, 2007). "The expression of Notch 1-EC protein was similar in benign and malignant tumours." (PMID 16136053, 2005). "Since GXYLT2 was previously shown to activate Notch1 signaling by up-regulating Hes family bHLH transcription factor 1 (HES1) to facilitate tumor progression, we investigated whether the suppressive effects of GXYLT2 knockdown on GC aggressiveness were related to Notch1 signaling." (PMID 41492474, 2026). "Additionally, the expression of NOTCH1 appears to vary according to tumor differentiation status." (PMID 41465166, 2025). "Finally, co-administration of a PD-L1 antibody with PEI-siYY1 represses HCC tumor growth without causing severe adverse effects, as observed with the Notch1 inhibitor DAPT." (PMID 41271562, 2025). "Moreover, we found substantial intratumor heterogeneity of NOTCH1-ICD expression, ranging from 1% and 80% of tumor cells, consistent with data from a prior IHC study of NOTCH1 in SCLC and the known intratumor heterogeneity of Notch signaling in SCLC mouse models." (PMID 40627448, 2025). "Thus, it has been demonstrated that NOTCH1 may inhibit tumor growth, but it could also play a part in early cancer development, probably by the promotion of epithelial–mesenchymal transition (EMT)." (PMID 41009728, 2025). "Therefore, Programmed Cell Death Ligand 1 (PD-L1) expression in NOTCH1 mutated tumors was significantly higher than in NOTCH1 wild-type tumors, therefore enriching the milieu in CD8+ T cells, hallmarks of a highly inflammatory tumor microenvironment." (PMID 40563292, 2025). "The result implies that concurrent activation of JAG1 or NOTCH1 downstream pathway with TGFβ signaling is important in the process of invasion and metastasis; however, it might be disadvantageous for the progression of the bulk of the tumor." (PMID 39074091, 2024). "However, several reports have pointed out to the possibility of Notch1 signaling may have a potent tumor suppressor role in both hematological malignancies and solid tumors and its activation may inhibit cellular growth." (PMID 38291201, 2024). "However, anti-tumor strategies targeting Notch1 all have side effects to varying degrees." (PMID 38866828, 2024). "Overall, these data support the selective inhibition of Notch1 to both bypass the gastrointestinal side effects and global immunosuppression associated with pan-Notch inhibition and most importantly, to maintain an anti-tumor CD8+ T cell population needed to kill the tumor cells." (PMID 39491031, 2024).